MICB (MHC class I polypeptide-related sequence B)
Diseases named in the same sentence as MICB in open-access papers (continued):
Sharing a sentence is not in itself a finding about the gene and the disease.
cervical cancer (7 papers, 2011 to 2025). A primary or metastatic malignant neoplasm involving the cervix. "It is consistent to our study that miR-940 was highly expressed in cervical cancer cell lines and cloud down regulate MICB expression in cancer cells leading to immune surveillance escape and surviving in the host." (PMID 28850101, 2017). "Firstly, we detected MICB mRNA expression levels compared with MICB surface protein expression levels on human cancer cell lines (cervical cancer and cholangiocarcinoma or CCA cell lines)." (PMID 28850101, 2017). "Our data on the preferential cell surface expression of MICA over MICB in SiHa cells are in agreement with a recent study examining activating NK ligands in various cell lines (including SiHa) and in tumor cells from patients with cervical cancer." (PMID 21631944, 2011). "Therefore, in the present study we performed a systematic analysis of the MICA and MICB expression in human cervical cancer cell lines." (PMID 21631944, 2011). "It is interesting to note that MICA and MICB has a greater induction for proliferation of the myelomonocytic cell lines than in the cervical cancer ones, we think that this is due to the fact that the myelomonocytic cells presented a higher expression of the NKG2D receptor on their membranes." (PMID 21477352, 2011). "This study provides evidence that even when MICA and MICB share a high degree of homology at both genomic and protein levels, differential regulation of their expression and cell surface appearance might be occurring in cervical cancer-derived cells." (PMID 21631944, 2011). "Thus, if high levels of soluble MICB are present in the serum of cervical cancer patients, and this contributes to tumor immune escape, targeting of this molecule could be a promising alternative to improve tumor immunosurveillance in these patients." (PMID 21631944, 2011). "We then performed IHC analysis of MICA/MICB, ULBP1, ULBP2, ULBP3, RAET1E, and RAET1G in 200 cervical cancer specimens, 327 high-grade CINs, 99 low-grade CINs, and 541 matched nonadjacent normal cervical epithelial tissue samples." (PMID 25510288, 2014). "We were further surprised when we found that epithelial human cervical cancer cell lines not only expressed MICA and MICB but also their receptor." (PMID 21477352, 2011). "The goal of this study was to describe the expression pattern of MICA and MICB at the molecular and cellular levels in human cervical cancer cell lines infected or not with human papillomavirus, as well as in a non-tumorigenic keratinocyte cell line." (PMID 21631944, 2011). "This study was focused on gaining a better understanding of MICA and MICB expression at the molecular and cellular levels in human cervical cancer cell lines infected or not with HPV and a non-tumorigenic keratinocyte cell line." (PMID 21631944, 2011). "However, metformin did not induce MICB, ULBP1, ULBP2/5/6 and ULPB3 expression on the surface of human cervical cancer cells." (PMID 32631421, 2020).
pancreatic cancer (7 papers, 2014 to 2026). "The Anti-MICB-CAR-NK cells hold considerable promise for the treatment of pancreatic cancer with high MICB expression." (PMID 41516373, 2026). "It was determined that Anti-MICB-CAR-NK cells co-treated with pancreatic cancer tumor cell line PANC-1 for 24 h secreted significant quantities of Anti-MICB-scFv and IL-15." (PMID 41516373, 2026). "We further verified that high glucose can promote the GATA2 to bind to the MICA and MICB promoter in pancreatic cancer under high glucose environment using ChIP assay." (PMID 31088566, 2019). "To explore the mechanism by which VPA upregulates MICA and MICB in pancreatic cancer cells, we examined the expression and activation of components of the HER2/HER3, ATM/ATR, and PI3K/Akt pathways." (PMID 24885711, 2014). "VPA enhances the susceptibility of pancreatic cancer cells to NK cell-mediated cytotoxicity both in vitro and in vivo by upregulating the expression of MICA and MICB via a PI3K/Akt signaling pathway-dependent mechanism." (PMID 24885711, 2014). "Our results demonstrate that VPA enhances the susceptibility of pancreatic cancer cells to NK cell-mediated lysis by upregulating the expression of MICA and MICB on pancreatic cancer cells." (PMID 24885711, 2014). "The expression of MICA and MICB in pancreatic cancer was significantly correlated with late TNM stage, tumor differentiation and lymphatic invasion." (PMID 24885711, 2014). "Our data demonstrates that VPA enhances the susceptibility of pancreatic cancer cells to NK cell-mediated cytotoxicity both in vitro and in vivo by upregulating the expression of MICA and MICB via activation of the PI3K/Akt pathway." (PMID 24885711, 2014). "Therefore, we analyzed the effect of VPA on the expression of MICA and MICB in pancreatic cancer cell lines." (PMID 24885711, 2014). "Although the role of PI3KCA siRNA on the expression of MICA and MICB protein was not totally compatible with its role on the NK cell-mediated lysis, the trend suggested that PI3K/Akt pathway played an important role in VPA-induced upregulation of MICA and MICB in pancreatic cancer cells." (PMID 24885711, 2014). "Moreover, we provide evidence to confirm that the VPA-induced upregulation of MICA and MICB in pancreatic cancer cells is dependent on the PI3K/Akt signaling pathway." (PMID 24885711, 2014). "Immunohistochemistry analysis revealed the MICA and MICB expression in pancreatic cancer." (PMID 24885711, 2014). "However, the present study demonstrated that inactivation of PI3K using LY294002 or a siRNA attenuated the ability of VPA to upregulate the expression of MICA and MICB in pancreatic cancer cells." (PMID 24885711, 2014). "In this study, we demonstrate that the expression of a novel Anti-MICB-CAR in natural killer (NK) cells results in significant in vitro cellular toxicity and in vivo tumor inhibition of PANC-1 human pancreatic cancer cells." (PMID 41516373, 2026). "In this study, gemcitabine upregulated the expression of MICB, ULBP1, ULBP2/5/6, ULBP3, and PVR in pancreatic cancer cell lines." (PMID 37169953, 2023). "In addition, this approach provides a meaningful theoretical basis for the treatment of solid tumors with Anti-MICB-CAR-NK cells and offers a potential pathway for the clinical treatment of solid tumors such as pancreatic cancer." (PMID 41516373, 2026). "We also examined the surface expression of MICA and MICB in pancreatic cancer cells treated with or without 1 mM VPA for 24 h." (PMID 24885711, 2014). "The NKG2DLs MICA and MICB play an important role in the NK cell-mediated lysis of cancer cells; therefore, we determined the effect of VPA on the expression of MICA and MICB mRNA in the human pancreatic cancer cell lines PANC-1, MIA PaCa-2, and BxPC-3." (PMID 24885711, 2014). "In order to explore whether VPA has potential as a treatment for pancreatic cancer, we examined the effects and mechanism of VPA action on the expression of MICA and MICB in human pancreatic cancer cells." (PMID 24885711, 2014).
pancreatic cancer (continued). "Thus, out of six different epigenetic modifiers tested, only HDAC inhibitor VPA increased cell surface expression and/or release of MICA, MICB and ULBP-2 from the pancreatic carcinoma and prostate carcinoma cell lines irrespective of their allelic MICA variation." (PMID 30972064, 2019).
autoimmune disease (6 papers, 2013 to 2025). A disorder resulting from loss of function or tissue destruction of an organ or multiple organs, arising from humoral or cellular immune responses of the individual to their own tissue constituents. "HCP5 is a vital lncRNA between the MICA and MICB genes in the MHC I region and is involved in many autoimmune diseases, including malignant tumors." (PMID 35571053, 2022). "Additional immune-regulatory loci include MICA/MICB, CTLA4, PTPN22, CIITA, CLEC16A, CD274 (PD-L1), and NLRP1 (NALP1)—variants shared with other autoimmune diseases, underscoring common immune checkpoints rather than AAD-specific genes." (PMID 41465179, 2025). "The source gene of lnc-HCP5 is located between MICA and MICB genes, which regulates the activities of various immune cells such as B cells, lymphocytes and NK cells, and plays an important role in HIV, AIDS, and various autoimmune diseases." (PMID 33194692, 2020). "The biological impact that soluble MICA and MICB might exert on the particular subset of CD4+NKG2D+ T cells is not well understood, but it has been proposed that pro-inflammatory cytokines may neutralize the NKG2D down-regulation induced by soluble MIC molecules in patients with autoimmune disease." (PMID 23947399, 2013).
HCMV infection (6 papers, 2010 to 2017). "In fact, MICA and MICB have been reported to be regulated by endogenous miRNAs in tumors and following cytomegalovirus infection." (PMID 26878797, 2016). "HCMV infection strongly induces transcription of MICB, ULBP1, and ULBP2 mRNA but prevents their surface expression by intracellular sequestration with HCMV UL16." (PMID 24906157, 2014). "Previously we showed that upon HCMV infection the virus downregulates the activating ligand MICB by the viral miRNA miR-UL112." (PMID 24586166, 2014). "A human cytomegalovirus (HCMV) miRNA acts synergistically with a cellular miR-376a to suppress one of the major histocompatibility complex class I polypeptide-related sequences (MICB) during HCMV infection." (PMID 21203544, 2010). "The NKG2DL MICB and ULBP2 are strongly upregulated during HCMV infection, but fail to reach the cell surface as they are retained in the ER by the NK evasion function gpUL16." (PMID 28186488, 2017). "This is because the anti-miR-376a(e) sponge does not antagonize MICB and because, as we have previously shown the anti-miR-376a sponge by itself is not sufficient to alter the levels of MICB during HCMV infection due to a synergistic interaction with the viral miR-UL112." (PMID 24586166, 2014). "We have also tested whether the sponges affect MICB expression following HCMV infection and observed that none of the sponges affect MICB expression during infection." (PMID 24586166, 2014). "At no stage during the replication cycle did HCMV infection induce an up regulation MICA, MICB, or ULBP2 expression at the cell surface." (PMID 24787765, 2014). "Because miR-376a(e) does not control the expression of MICB and since we showed that ADAR1-p110 is strongly induced specifically upon HCMV infection leading to increase levels of miR-376a(e)." (PMID 24586166, 2014).
asthma (5 papers, 2014 to 2024). "Here, we determine the relationship between MICA and MICB and RV infection in vitro in respiratory epithelial cells and in vivo in healthy subjects and subjects with asthma." (PMID 24556715, 2014). "The present study is, to our knowledge, the first investigation of the potential role of MICA and MICB molecules in the pathogenesis of RV infection in healthy subjects and subjects with asthma." (PMID 24556715, 2014). "Relatively high genetic prediction levels of MICB (OR = 0.9984; 95% CI, 0.9979–0.9989; p = 1.04 × 10−9) and PDE4D (OR = 0.9980; 95% CI, 0.9972–0.9987; p = 1.89 × 10−7) were observed to reduce the risk of asthma in children." (PMID 38730525, 2024). "Induction of MICB molecules is impaired in subjects with asthma, suggesting these molecules may have a role in the antiviral immune response to RV infections." (PMID 24556715, 2014). "The indirect effects of MICB, PDE4D, and IL‐21 on childhood asthma via BMI were relatively modest, at 3.31%, 5.03%, and 3.43%, respectively." (PMID 38730525, 2024). "Moreover, the indirect effects of MICB, PDE4D, and IL‐21 on childhood asthma via BMI are relatively modest, at 3.31%, 5.03%, and 3.43%, respectively." (PMID 38730525, 2024). "Our study showed MICB mRNA expression to be increased during HRVI in children without asthma compared to the children with asthma." (PMID 30485264, 2018). "Following RV infection, airway levels of sMIC are upregulated, and there are positive correlations between sputum MICB levels and the percentage of bronchoalveolar natural killer cells in healthy subjects but not subjects with asthma." (PMID 24556715, 2014). "This suggests that MICB, PDE4D, and IL‐21 plasma proteins do not influence the occurrence of childhood asthma through BMI." (PMID 38730525, 2024). "This suggests that MICB, PDE4D, and IL‐21 proteins do not influence the occurrence of childhood asthma through BMI." (PMID 38730525, 2024).
leukemia (5 papers, 2016 to 2022). A malignant (clonal) hematologic disorder, involving hematopoietic stem cells and characterized by the presence of primitive or atypical myeloid or lymphoid cells in the bone marrow and the blood. "We examined the expression of NKG2D ligands in leukemia cell lines treated with low concentration AACOCF3 (5μM) and found that expression levels of the MICA, MICB, and ULBP family were all significantly elevated." (PMID 36338749, 2022). "Exosomes from solid tumors or leukemia/lymphoma cells can present MICA, MICB, and ULBP molecules leading to an inhibition of the NKG2D-mediated NK cell activation." (PMID 27014273, 2016). "The lack of NKG2D ligands (MICA, MICB, or others) is a trait of resistant leukemia stem cells." (PMID 32516941, 2020).
colon carcinoma (4 papers, 2019 to 2022). "BCL11B up-regulates NKG2D ligands of the major histocompatibility complex class I-related molecules A and B (MICA and MICB), promotes the anti-tumor response of T- and NK-cells and prevents immune evasion of colon cancer cells." (PMID 36600891, 2022). "In contrast, upregulation of MICA and MICB (MHC class I polypeptide-related sequence B) gene expression has been reported in CaCo-2 colon carcinoma cell line upon oxidative stress, an effect that could strengthen NK cell recognition and tumor cell elimination." (PMID 31535086, 2019). "In stratified analysis according to tumor location, for patients with right-sided or left-sided colon cancer, MICB expression was not a significant prognostic factor." (PMID 32306128, 2020).
endometriosis (4 papers, 2015 to 2025). The growth of functional endometrial tissue in anatomic sites outside the uterine body. "In a similar manner peritoneal fluid MICB levels were also increased in endometriosis-affected patients compared with disease-free women (median, 4.6 pg/mg; range, 1.2–4702 versus median, 3.4 pg/mg; range, 0.7–20.1; p=0.001)." (PMID 25775242, 2015). "Our study shows that MICB levels are significantly elevated in peritoneal fluid of patients with endometriosis as compared to endometriosis-free women, especially in those patients with the most severe forms of the disease." (PMID 25775242, 2015). "MICB resulted positive in 118 (97.5%) patients with endometriosis and in 78 (96.3%) endometriosis-free patients (P = 0.685)." (PMID 25775242, 2015). "From the Cancer Hallmarks perspective, GATA4, C2, MICB, and CLDN23 were implicated in evading immune destruction and tissue invasion, suggesting that even within intestinal tissues, relevant molecular signals associated with the pathophysiology of endometriosis may be present." (PMID 40863222, 2025). "Statistical analyses for peritoneal NKG2D ligands (MICA, MICB and ULBP-2) ratio levels in women with endometriosis and controls." (PMID 25775242, 2015). "Clinical, surgical and biological correlations with peritoneal fluid MICA, MICB and ULBP-2 levels in women with endometriosis are expressed in S3 Table." (PMID 25775242, 2015). "For this reason, we assayed peritoneal fluid NKG2DLs (MICA, MICB and ULBP-2) obtained from patients with histologically proven endometriosis and endometriosis-free women." (PMID 25775242, 2015). "When samples with undetectable peritoneal fluid levels of MICA, MICB and ULBP-2 were excluded, MICA ratio levels were significantly higher in endometriosis patients than in controls (median, 1.1 pg/mg; range, 0.1–143.5 versus median, 0.6 pg/mg; range, 0.1–3.5; p=0.003)." (PMID 25775242, 2015).
Graves disease (4 papers, 2020 to 2025). Graves' disease is an autoimmune disorder that leads to overactivity of the thyroid gland (hyperthyroidism).It is caused by an abnormal immune system response that causes the thyroid gland to produce too much thyroid hormones. "In addition, elevated levels of MICB were associated with increased risks of various metabolic disorders, including thyrotoxicosis, type 1 diabetes, and various forms of hypothyroidism, including NOS and Graves’ disease." (PMID 38049731, 2023). "Furthermore, genetically higher plasma levels of IL‐21 and MICB are associated with an elevated risk of digestive disorders such as intestinal malabsorption and endocrine metabolic disorders including Type 1 diabetes, thyrotoxicosis with or without goiter, and Graves' disease." (PMID 38730525, 2024).
vitiligo (4 papers, 2018 to 2025). Generalized well circumscribed patches of leukoderma that are generally distributed over symmetric body locations and is due to autoimmune destruction of melanocytes. "Next we performed MICA/MICB immunofluorescence staining on sections from vitiligo and control biopsy samples together with the melanocyte marker TYRP1." (PMID 30515176, 2018). "The upregulation of stress-ligand MICA/MICB, recognized by activating receptors on innate and innate-like T cells, imply involvement of lymphoid stress surveillance responses in vitiligo lesions." (PMID 30515176, 2018). "Notably, the stress molecule MHC class 1 chain-related protein A and B (MICA/MICB) that can be bound by activating NK cell receptors also showed a tendency for increased expression in vitiligo lesions (p = 0.052)." (PMID 30515176, 2018). "Moreover, PGZ significantly lowered gene expression levels of stress molecule MHC class 1 chain-related protein A and B (MICA/MICB), NKG2D ligands, whose role was recently described in vitiligo pathogenesis." (PMID 36429011, 2022). "We could clearly observe staining for MICA/MICB in dermal areas of vitiligo lesional skin but not in healthy or non-lesional skin." (PMID 30515176, 2018).
COVID-19 (3 papers, 2021 to 2025). A disease caused by infection with severe acute respiratory syndrome coronavirus 2. "When evaluating COVID-19[+] and COVID-19[-] individuals from the same sex, we observed that the susceptibility MICB variants are overrepresented in symptomatic men and women, but significant only among men (p = 0.0128)." (PMID 34650566, 2021). "A recent study showed the association between MICB G406A polymorphism and COVID-19 severity." (PMID 41153412, 2025). "Among MHC genes, we identified a significant association between MICB and COVID-19[+] (p = 0.017)." (PMID 34650566, 2021). "As for MICB, the rs1065075 SNP could potentially be linked to COVID-19 severity." (PMID 41153412, 2025). "Host genetics influencing NK cell activation due to differential expression of MICA and MICB is another layer in the complex interaction between the human genome and COVID-19 outcome." (PMID 34650566, 2021). "In the future, demonstrating MICB-driven differences in abundance and functionality of NK cells in the lung longitudinally during COVID-19, ideally starting from the onset of symptoms, would help develop interventions that can exploit this pathway in preventing the most critical outcomes." (PMID 40608426, 2025). "Results obtained within this study indicate that the presence of deletion within the NKG2C/KLRC2 gene, as well as NKG2A rs7301582, HLA-E rs1264457, MICB rs065075, and MICA rs1051792 SNPs, could be associated with COVID-19 susceptibility and the severity of the disease." (PMID 41153412, 2025). "Functional assays will provide the means to test the hypothesis of differential NK cell activity between COVID-19 symptomatic and asymptomatic exposed individuals, involving MICA and MICB." (PMID 34650566, 2021).